MKI67 (marker of proliferation Ki-67)
Diseases named in the same sentence as MKI67 in open-access papers (continued):
Sharing a sentence is not in itself a finding about the gene and the disease.
tumor (continued). "Moreover, DR5 expression was also related to the expression of MKI67 and CD44, and stemness index (mRNAsi), which revealed the correlation between DR5 and tumor stemness." (PMID 37879960, 2023). "A previous study based on different syngeneic tumor models has shown that CD8+ T cells co-expressing inhibitory receptors (IRs) are not dysfunctional, but rather highly express activation and effector-related marker genes such as IFNG, GZMB, MKI67, and ICOS." (PMID 37773254, 2023). "Expression of each of these proliferative markers (PCNA, MKI67, and HDAC1) positively correlated with that of KSR2, indicating KSR2 may promote tumor proliferation." (PMID 35468812, 2022). "BC is further classified into several subclasses, characterized by immunohistochemical staining {(e.g., ER, PR, HER2 (ERBB2)}, proliferation marker protein Ki-67 (MKI67), genomic markers (e.g., BRCA1, BRCA2, and PIK3CA), and immunomarkers (e.g., tumor-infiltrating lymphocytes and PD-L1)." (PMID 36232989, 2022). "Using data retrieved from our previous study, we demonstrated that the gene expression level of KRT13 was significantly down-regulated in OSCCs compared to their corresponding non-tumor epithelia, while the expression levels of KRT17, MKI67, and LAMC2 in OSCCs were significantly upregulated." (PMID 35524231, 2022). "In addition, consistent with the primary tumor, P1 and P2 PDX models also maintained elevated MKI67 mRNA expression." (PMID 35928724, 2022). "Changes to levels of FoxP3+ and MKi67+CD8+ cell densities between baseline (BL) and on treatment (OT) tissue samples provide an early signal of anti-tumor activity and can validate the hypothesized mechanism of action." (PMID 35558070, 2022). "Although the effects of proliferative MKI67+ CD4Ts/Tregs on ICB outcomes have been reported in other tumor types, this correlation has not been documented in ccRCC before." (PMID 36091022, 2022). "Subsequently, we analyzed SQLE expression and its association with biomarkers of MHC (B2M, HLA-B, HLA-C, TAP1, and TAP2), dendritic cells (BATF3), macrophages (CD68 and IL1A), type-I anti-tumor responses (CD8A and GZMB), and cell proliferation (MKI67) in 178 PAAD tissues." (PMID 35720314, 2022). "We measured MKI67 mRNA expression in tumour and noncarcinoma samples from distinct cancers based on the Oncomine database to determine the differential MKI67 expression between cancer and noncarcinoma samples." (PMID 34724892, 2021). "There is also a strong positive correlation between WDR62 expression and MKI67, a marker of cell proliferation in mCRPC samples suggesting WDR62 could drive tumor cell proliferation or survival." (PMID 34326322, 2021). "Taken together, the scRNA-seq analyses of tumor cells revealed the intratumoral heterogeneity of 4T1 allograft, and that treatment of CYH33 resulted in cell cycle arrest and a decrease in highly proliferative Mki67+ cells in immune-competent mice." (PMID 34373258, 2021). "In contrast, BAMBI and TNFRSF19 positive cells from primary tumor sections did not express or only minimally expressed MKI67." (PMID 33898197, 2021). "Notch2 could promote tumor proliferation through regulating the levels of MYC (r = 0.8, P < 0.001) and MKI67 (r = 0.89, P < 0.001)." (PMID 33425722, 2020). "Crucially, HK2 prognostic value was independent of tumor proliferation as assessed by multivariate cox analysis using MKI67, ESR1 and HER2 expression levels." (PMID 32164162, 2020). "In addition to MCM2-7 complex, other proteins in the cluster also influenced the growth and division of tumor cells by participating in the cell cycle such as RRM2, PRKAR2B, and MKI67." (PMID 33200655, 2020).
tumor (continued). "On the one side, we reveal that TB shares a set of potential pathogenic mediators with LUAD or sarcoidosis, and further demonstrate that host MKI67, an over-expressed gene shared by TB and LUAD, is involved in Mtb-promoted tumor cell proliferation, migration, and invasion." (PMID 33097805, 2020). "The ACS-HN11 tumour model had the highest pimonidazole-positive hypoxic fraction as well as the highest MKI67, POR and SLFN11 expression, but was also p16-positive, thus an ~85–90% likelihood of being HPV-positive, and originated from a tumour that was recurrent post chemoradiotherapy." (PMID 31337055, 2019). "Our data suggest that evofosfamide sensitivity cannot be robustly predicted by hypoxia, MKI67, POR, or SLFN11 expression on their own, but rather is likely to be multifactorial, incorporating tumour hypoxia and other genes that influence the activation and mechanism of action of evofosfamide." (PMID 31337055, 2019). "The expression specific for tumour cells and CD8+ T cells estimated using RESPECTEx were in broad agreement with mean expression levels in MKI67+ single cells (for tumour) and CD8A+ single cells (for CD8+ T cells), confirming the validity of inferences by the RESPECTEx pipeline." (PMID 30624727, 2019). "Tumor cell content, DCIS content, HER2 immunohistochemical score of the invasive tumor and the DCIS, as well as relative expression of the mRNA markers ERBB2, ESR1, PGR and MKI67 and absolute Δ40-ddCq values are shown." (PMID 30342538, 2018). "Subsequent measurement of tumor biomarker mRNA expression to detect conversion revealed significant decreases in ESR1 and PGR mRNA and MKI67 upregulation (all p < 0.001) in MT compared to PT of all tumor subtypes and ERBB2 upregulation in MT from triple-negative PT patients (p = 0.023)." (PMID 28881657, 2017). "Concordance was 100 % for ERBB2, ESR1, PGR whereas for MKI67, one case containing 10 % tumor cells was negative in the non-macrodissected sample." (PMID 27389414, 2016). "In ER negative tumours however, regardless of the classifiers applied, MKI67 manifested no significant prognostic power." (PMID 21152022, 2010). "We found that high expression of MKI67 was correlated with poor differentiation, TNM classification, and classification in BRCA patients, and high expression of MKI67 was closely related to BCLA stage, Edmondson grade, tumor size, and tumor nodule increase in LIHC patients." (PMID 40070823, 2025). "The expression levels of growth factor receptor genes (EGFR and ERBB2) and proliferation marker genes (PCNA and MKI67) in epithelial cells were not significantly higher in unaffected lung samples adjacent to a focal tumor compared with samples originating from healthy lungs." (PMID 40114924, 2025). "Additionally, the presence of proliferative MKI67+ T cells was exclusive to TNBC patients experiencing disease progression after chemotherapy, and their gene expression correlated with lymph node metastases, tumor invasion, and adverse survival outcomes." (PMID 40858590, 2025). "Interestingly, though hot tumors were associated with increased proliferation (bulk MKI67 protein), MKI67 percentage according to IHC that only counts tumor cells was not different between the three immune states at baseline." (PMID 38714665, 2024). "Additionally, the tumor sample contained various other cell types, including epithelial cells (EPCAM+), pStr (MKI67+) CD4+T cells (CD4+), CD8+ T cells (CD8A+), macrophages (CD68+), and regulatory T cells (FOXP3+), which were further validated by our single-cell data." (PMID 39676856, 2024). "Similarly, the expression of genes for cell differentiation (CAV1 for caveolin-1) and cell proliferation (MKI67 for marker of proliferation Ki-67 and PCNA for proliferating cell nuclear antigen) were down- and upregulated, respectively, in tumor samples (adjusted p value < 0.01)." (PMID 39062740, 2024).
tumor (continued). "Studies have found that tumour epithelial cells expressing specific markers (such as SOX9 and MKI67) exhibit stem cell‐like characteristics, possessing the potential for self‐renewal and differentiation, and may play a key role in the occurrence, development and metastasis of cancer." (PMID 39443302, 2024). "In addition, a substantial portion of tumor cells and non-tumor cells expressed Mki67, indicative of their proliferative status." (PMID 36929001, 2023). "Notably, tumor ECs were featured by upregulation of angiogenesis-related genes including collagens (e.g., COL4A1, COL4A2), PXDN, SPARC and HSPG2, as well as proliferation markers (e.g., MKI67, TOP2A)." (PMID 36138435, 2022). "In addition, the expression of the cell proliferation markers AURKA, AURKB, CCNB1, and MKI67 was higher in the patients’ tumor tissues than those of normal tissues." (PMID 34503223, 2021). "High proliferative goblet cells expressing MKI67 and metaplastic paneth cells expressing antimicrobial α‐defensins (DEFA5 and DEFA6) were enriched in precancerous and tumor tissues comparing with adjacent tissues, suggesting they might play a role in tumorigenesis." (PMID 34185431, 2021). "In addition, we found that the expression levels of T-cell exhaustion-related genes including CD40, GRB2, MKI67, NFATC3, PRDM1, TCF7, and TGFB1 were significantly higher, while those of CXCR5 and TOX were significantly lower after tumor recurrence (all p < 0.05)." (PMID 34305618, 2021). "Interestingly, a subset of these tumor-associated CD8+ T cells, but not healthy T cells, express high levels of MKI67, associated with proliferating cells and other cell cycle control markers." (PMID 31624246, 2019). "Moreover, the GTSE1 mRNA expression level is positively correlated with MKI67, which was consistent with the results of the protein level, suggesting that GTSE1 may be a potential tumor marker for prognosis." (PMID 30961661, 2019). "Thus, the impact of TCC on RNA relative quantification is gene-specific and as far as MammaTyper® genes ERBB2, ESR1, PGR and MKI67 are concerned the bias introduced by the inclusion of tissue surrounding the invasive tumor appears to be non-critical." (PMID 30342538, 2018). "Il6 deficiency also reduced hepatic mRNA levels of Stat3 target genes (Birc5, Bcl2l1 and Ccnd1), cyclins (Ccna2, Ccnb1, Ccnb2), and markers of proliferation (Mki67) and HCC (Afp) in livers from FGF19-expressing mice, further demonstrating the role of IL-6 in mediating FGF19-driven tumour growth." (PMID 28508871, 2017). "Responders (patients with high tumor regression) showed a significantly lower MKI67 expression than nonresponders in the pretherapeutical tumor biopsies (81.2% versus 16.7%; p < 0.05) as well as in the posttherapeutical resection specimens (75.8% versus 14.3%; p < 0.01)." (PMID 27610130, 2016). "Interestingly, despite the lower circRNA index in miliary PM samples, proliferation (MKI67 expression) was not elevated in miliary compared to non-miliary tumor cells." (PMID 27172797, 2016). "In order to evaluate the effect of FA + ASP chemopreventive regimens on tumor cell proliferation, immunohistochemistry (IHC) was performed to measure the expression of cell proliferation markers proliferating cell nuclear antigen (PCNA) and MKI67 on pancreatic tissues." (PMID 26301084, 2015). "In addition, the immunohistochemical analysis of tumor tissue showed significant decrease in expression of proliferation proteins PCNA and MKI67, and also increased expression of apoptotic proteins p-RB, p21, and p-ERK1/2 indicating the pro-apoptotic role of the regimen." (PMID 26301084, 2015). "GEP studies have consistently identified at least two groups of ER+ tumours; the less favourable LB group being characterised by higher histological grade and higher expression of proliferation and HER2-related genes, such as MKI67, MYBBL2, CCNB1, HER2 and GRB7, and lower levels of ER-related genes." (PMID 21712826, 2011).
tumor (continued). "To verify that the ER status-dependent prognostic power of proliferation is not affected by bias in tumour stage, we combined the ER calls in the four reference cohorts and performed a multivariate Cox regression based on lymph-node status, ER status, MKI67 expression and their interaction." (PMID 21152022, 2010). "Finally, analysis of polysomal RNAs from livers of CTL and TIA1 knockdown LPTENKO mice indicated that consistent with a lack of effect of TIA1 downregulation on tumor growth and progression, markers for proliferation (Mki67, Pcna, Cdkn1a, Cdkn1b, Cdc25a) and inflammation (Il1b, Tgfb) were unchanged." (PMID 35406476, 2022). "Interestingly, the patient (CS-BS-00141) in which two tumor specimens with high transcriptomic grade, and two other tumor pieces had low transcriptomic grade, exhibited intra-tumor variability only in MKI67 expression but not in ER, PR or HER2 gene expression values." (PMID 29187174, 2017). "While the marker of proliferation, MKI67, was increased in tumor samples, DIPG tumor samples showed no significant upregulation of immune checkpoint markers PD-L1 (CD274) and CTLA-4 compared to matched normal tissue." (PMID 41541220, 2026). "While the initiating cells in recurrent tumors were mainly related to the cell cycle such as MKI67, CKS2, ANLN, CDC20, CDCA8, CENPF, inflammatory signals no longer drive anti-tumor immunity." (PMID 41601649, 2026). "The macrophage lineage was further divided into predominant populations: suppressive (SPP1+, APOC1+), pro-tumour (VEGFA+, MKI67+), inflammatory (C1QC+), classical (CD14+) and non-classical cells (CD16+)." (PMID 39788719, 2025). "While circadian magnitude offers prognostic value beyond PAM50 tumor type and MKI67 transcript expression, we do not have immunostained Ki-67 protein levels in these TCGA samples." (PMID 38319971, 2024). "Additionally, Mki67-positive CD8+ T cells may contribute to the formation of immune memory, enabling the cells to better respond to the same antigen upon re-encounter, thereby maintaining long-term anti-tumor immune effects and preventing tumor recurrence and metastasis." (PMID 38280084, 2024). "Particularly, They show high expression of cell proliferation-related genes MKI67 and TOP2A, but tumor stem cell marker genes CD44 and CD133 were not highly expressed." (PMID 37880655, 2023). "High MKI67 signal was restricted to the tumour cells of the interface located in close proximity to Gfap-positive astrocytes, which were mostly absent in the bulk of drug-treated PDOX comprising MKI67-negative tumour cells." (PMID 37127652, 2023). "Intriguingly, Pladienolide-B did not influence the expression of genes relevant to tumor biology (apoptosis, proliferation, inflammation) in MIAPaCa-2 cells or in HPDE E6E7 cells, including NFKB1, CASP3, MKI67, and HER2." (PMID 34857016, 2021). "MKI67 is a well-known marker of cell proliferation, expressed both by tumor and nontumor cells, clinically determined by MIB1 or Ki67 IHC staining of WSIs." (PMID 32747659, 2020). "5-Aza-CdR interestingly decreased levels of genes that promote tumor progression, such as CCND1, MKI67, BIRC5, and BCL2, but failed to decrease MUC4 and NOTCH1." (PMID 32182826, 2020). "Non-significant differences were observed among treatments in the tumor growth nor in HMOX1, BCLXL, IKBA, and MKI67 gene expression." (PMID 30813528, 2019). "In univariate analyses, lymph node positivity, surgical margin positivity, non-localized tumor, age at prostatectomy, and biomarkers CCND1, HMMR, IGF1, MKI67, SIAH2, and SMAD4 in malignant epithelium were significantly associated with time to BF." (PMID 24708576, 2014).
tumor (continued). "The role of Ki-67 as a proliferation marker in HCC has been reinforced by recent transcriptomic analyses, which demonstrated that high Ki-67 gene expression (MKi67) correlates with histologic progression from cirrhotic liver to advanced HCC, independent of tumor grade." (PMID 40941632, 2025). "In parallel, although CYH33 did not downregulate the percentage of Krt18+ cells, the proportion of Mki67+ cluster in Krt18+ cells decreased in Balb/c mice but not in nude mice on CYH33 treatment, indicating that tumor cells are less proliferative in immune-competent mice." (PMID 34373258, 2021). "Furthermore, its negative correlation with MKI67 expression and LUAD differentiation indicated the tumor-suppressor activities." (PMID 32265992, 2020). "The other cell cycle genes analyzed (PLK1, FOXM1, MKI67) were downregulated in romidepsin-treated spheres and PDX-Os but were not changed after romidepsin treatment of the cell line (FOXM1 was increased in the cells) nor tumor implants." (PMID 33035223, 2020). "CK19 antibodies undoubtedly mark only the epithelial tumour cells (Panc1, HPAFII) but not the hPSCs, thus making it possible to separate the two cell types in the co-cultures and to determine their proliferation by MKI67 double-staining." (PMID 32460715, 2020). "Examining the same genes in CCND1-amplified vs. non-amplified luminal A tumours showed increased MKI67 and decreased PGR gene expression in amplified tumours (see “MKI67” and “PGR”, P < 0.001 and P = 0.002 respectively), consistent with a more aggressive phenotype." (PMID 30819233, 2019). "The relative expression levels of CDKN3, MKI67, CEP55, SPAG5, AURKA, TOP2A were consistent with the results of bioinformatics analysis (P < 0.05), while the expression levels of UBE2C, CHEK1 and BIRC5 in tumor samples were not significantly different from adjacent normal samples." (PMID 35178291, 2022).